HIF1A (hypoxia inducible factor 1 subunit alpha)
Diseases named in the same sentence as HIF1A in open-access papers (continued):
Sharing a sentence is not in itself a finding about the gene and the disease.
tumor (continued). "The mechanism behind the involvement of HIF-1α in metastasis, tumor progression and chemotherapy resistance is due to the resultant overexpression of VEGF and MDR1." (PMID 30746305, 2019). "To investigate the role of BAP1 independently of chromosome 3 status, we analysed the association between BAP1 and HIF1a/VHL within the D3 and M3 tumours separately." (PMID 31323773, 2019). "The transcriptional complex of XBP1 with HIF1α elevates the expression of pyruvate dehydrogenase kinase 1 (PDK1) and glucose transporter 1 (GLUT1) that are the downstream genes of HIF1α, which facilitates tumor development and invasiveness of TNBC." (PMID 31739582, 2019). "The authors also showed less drug accumulation in tumour spheroids than monolayer cells, and attributed this doxorubicin resistance in part to the activation of HIF-1α, which can occur at 3% oxygen." (PMID 31780697, 2019). "In tumor cells there is evidence that hypoxia causes a rapid activation of SPHK1, preceding HIF-1α accumulation." (PMID 31379883, 2019). "The heat-shock 70-kDa protein-1-like (HSPA1L) gene is pivotal in tumor niche condition-induced HIF-1α activation and cellular prion protein (PrPC) regulation and leads to CRC proliferation." (PMID 30755640, 2019). "Taken together this suggests important roles for HIF-1α in tumor progression and development of antiestrogen treatment escape mechanisms." (PMID 31821370, 2019). "In hypoxia, HIF1α stable existence and activation allow tumor cells to adapt to hypoxia and survival." (PMID 30082910, 2019). "VHL is a tumor suppressor protein, because its interaction with HIF-1α leads to the recruitment of an E3 ubiquitin ligase, targeting HIF-1α to the proteasome and its degradation." (PMID 30708988, 2019). "Recent reports suggest that sorafenib treatment can elicit hypoxic to activate HIF-1α in tumor cells and stromal cells in tumor microenvironment, leading to increases in expressions of CXCR4 and its ligand SDF-1α in HCC." (PMID 31151472, 2019). "We found that HIF-1α-positive tumor areas tended to be larger in the AMD3100 group than those in the control group." (PMID 31336612, 2019). "As such, both O-GlcNAc modifications and HIF-1α transcriptional activity emerge as key metabolic modulators, while stromal cells promote a metabolic symbiosis with tumor cells envisaging tumor survival and growth." (PMID 31157165, 2019). "Hypoxic conditions stabilize hypoxia-inducible factor-1 alpha (HIF-1α) protein, which has been reported to be a cause of tumor resistance to therapeutic mechanisms." (PMID 31569523, 2019). "HIF-1α has been shown not only to increase intravascular tumor microvascular density in xenografts but also to overexpress in RCC." (PMID 31466366, 2019). "On the other hand, tumor hypoxia and HIF-1α activation in tumor cells promote glycolysis, increasing glucose uptake by proliferating tumor cells." (PMID 31083487, 2019). "This would increase intratumoral drug perfusion, while concurrently impeding the adaptive fitness of tumour and stromal cells to survive under hypoxic conditions (via HIF-1α) and thus promote widespread hypoxic necrosis." (PMID 30575816, 2019). "Incubation under hypoxic conditions (0.1% oxygen), as can be found in the tumour microenvironment, triggered HIF-1α stabilisation and induced DDIT4 gene expression and protein with decreased phosphorylation of RPS6 as evidence for mTORC1 inhibition." (PMID 30745581, 2019). "HIF-1α plays an important role in the survival, growth and metastasis of tumor cells, suggesting that HIF-1α inhibitors possess effective effect for tumor treatment." (PMID 31022939, 2019). "Preclinical studies have demonstrated the potential to pharmacologically block both HIF-1α and/or HIF-2α, causing tumor growth delay and improved local control." (PMID 30642030, 2019). "HIF-1α, a transcription factor, is often induced by an intratumoural hypoxic microenvironment and is closely related to tumour angiogenesis, metastasis, and growth." (PMID 30911001, 2019).
tumor (continued). "and the expression of HIF-1α negatively correlates to ERα status and positively correlates to tumor grade." (PMID 30940798, 2019). "Direct IHC analysis of the post-surgical specimens showed robust staining of CA-IX and GLUT-1, both downstream targets of HIF-1α, independently confirming the presence of tumor hypoxia." (PMID 31766580, 2019). "Clinically, evaluation of EZN-2968 treatment of 4 out of 6 patients with paired tumor biopsies showed reduced HIF-1α mRNA in posttreatment biopsies while two patients had a reduced level of mRNA and HIF-1α protein of target genes in biopsies." (PMID 31485300, 2019). "The reduced PML levels lead to a derepression of mammalian target of rapamycin (mTOR), which in turn participates in a feedback mechanism to amplify HIF-1α signaling, thus facilitating tumor progression." (PMID 31208103, 2019). "A hypoxic microenvironment has been described to play a central role in the increase of ROS in tumor, through the activation of the hypoxia-inducible factor 1 alpha (HIF-1α) and its target genes." (PMID 31934266, 2019). "The hypoxia-inducible factor-1α (HIF-1α) signaling pathway plays a vital role in blood microcirculation disorders including ischemic, hypoxia, inflammation, and tumor angiogenesis." (PMID 31320912, 2019). "HIF1A also increases the expression of multiple enzymes involved in glycolysis, which further aids tumor cell growth and proliferation." (PMID 31744467, 2019). "The IDH1 mutant also seems to induce the NF-κB pathway in an HIF1-α dependent manner, regulating tumor cell proliferation." (PMID 30708988, 2019). "Activated HIF-1α has a crucial role in the adaptive response of tumor cells to oxygen conditions in their microenvironment." (PMID 30708988, 2019). "Previous experiments in ESCC have suggested that HIF-1α signaling pathway’s suppression with berberine, led to tumor radiosensitization." (PMID 31739546, 2019). "The transient increase of HIF-1α seen in whole lung tissue following acute hypoxia correlates with increased tumour numbers, transient increases in pulmonary microvessel permeability and iNOS expression." (PMID 31308473, 2019). "The results showed that, after laser irradiation, the HIF-1α expression in the PNP-treated tumours was much higher than that in the control groups." (PMID 30952842, 2019). "Pimonidazole and HIF-1α staining showed that PNP-treated tumours were more hypoxic than tumours in the control groups even at 24 h after irradiation." (PMID 30952842, 2019). "In many types of cancer, HIF-1α is the vital regulator in tumor growth and angiogenesis, which is induced by hypoxic environment and oncogenic mutations to enhance VEGF production." (PMID 30804329, 2019). "Among all HIF-1α mediated proteins, CAIX (a carbonic anhydrase), is one of the most promising tumor-associated proteins in the carcinogenesis process of OSCC." (PMID 30654595, 2019). "We also confirmed that ALM induces tumor cell apoptosis in vitro and inhibiting tumor xenograft in vivo, by inhibiting HIF-1α." (PMID 31083403, 2019). "In our model, these data are supported by the downregulation of VEGF-A165 and HIF-1α expression observed in LOX-1RNAi tumor, demonstrating a direct link among LOX-1, VEGF-A165, and neo-angiogenic process involved in tumor formation and progression." (PMID 31608230, 2019). "SLC4A4 mRNA expression depends exclusively on hypoxia inducible factor 1 subunit alpha, a tumor suppressor gene in ccRCC." (PMID 30668544, 2019). "Consistent with the tumor growth data, Western blot analysis demonstrated that HIF-1α protein was reduced in xenografts treated by ALM combined with Everolimus." (PMID 31083403, 2019). "Surprisingly, clinical studies of tumor-derived tissue demonstrated only a weak correlation between the amount of HIF-1α expression and oxygen levels." (PMID 31035491, 2019).
tumor (continued). "Because hypoxia-inducible factor 1α (HIF1α) is the major regulator of tissue oxygen homeostasis and HIF1α expression closely correlates with tumor growth and invasion, HIF1α is considered to be responsible for hypoxia-mediated cancer progression." (PMID 30082910, 2019). "In terms of the HIF1α signaling pathway, it is well-known that hypoxia is a strong stimulus for tumor metabolism, growth, and progression." (PMID 31109060, 2019). "Hypoxia-inducible factor 1α (HIF-1α) is a key stress-responsive transcription factor to low oxygen; the expression of HIF-1α is associated with tumor progression and angiogenesis." (PMID 30678221, 2019). "Meanwhile, increased HIF-1α decreases tumor latency, increases vascular density, tumor volume, permeability, and growth." (PMID 31350968, 2019). "In another study on ovarian cancer cells, Xia and colleagues documented that NOX4 knockdown lead to a reduction of VEGF and HIF-1α, which in turn regulated tumor angiogenesis." (PMID 31766246, 2019). "Mice exposed to acute hypoxia, showing the highest lung HIF-1α levels, had more tumours than the controls breathing room air, whereas mice exposed to chronic hypoxia developed lung tumours in numbers similar to those found in normoxic controls." (PMID 31308473, 2019). "The expression of HIF1α was significantly increased in tumor tissue after treatment with ZIR700, which reflects tumor hypoxia." (PMID 33568892, 2019). "miR-210, induced by HIF-1a, is overexpressed in tumor cells and in the tumor microenvironment and shows an inverse correlation with survival in patients with breast cancer." (PMID 31500658, 2019). "Activation of HIF-1α plays an important role in promoting tumor angiogenesis, growth and metastasis." (PMID 31041568, 2019). "The presence of HIF-1α and HIF-1β was shown to be proportionally associated with the grade of tumor progression, a characteristic that was described for gliomas." (PMID 31396523, 2019). "For instance, HIF1α induces the expression of the inhibitory immune checkpoint regulator programmed death-ligand 1 (PD-L1), which facilitates the suppression of anti-tumor immune effects." (PMID 31866995, 2019). "Altogether, these findings fully support that FN can be reexpressed in tumor cells under hypoxic conditions either by HIF1α-dependent or -independent signaling regulations." (PMID 31861892, 2019). "GPC3 knockdown significantly suppressed the tumor growth and metastasis of LC cells, while forced expression of HIF-1α significantly reversed these effects." (PMID 31781603, 2019). "In order to evaluate the hypoxia induction we first examined the expression of HIF-1α and its associated gene like VEGF as the hypoxia is well known inducer of angiogenesis which is necessary for tumor progression." (PMID 30876462, 2019). "HIF-1α protein was detected in 94% (49/52) of tumor samples, and levels were significantly increased compared with the matched normal tissue sample (p < 0.001, paired t-test)." (PMID 30943919, 2019). "On the one hand, overexpression of PHD1 was shown to decrease tumor growth in a murine xenograft model by reduction of HIF1α and VEGF levels." (PMID 31404997, 2019). "Microvascular invasion accelerates the release of tumor angiogenesis-promoting factors, such as hypoxia-inducible factor α (HIF1α) and vascular endothelial growth factor (VEGF), and diversifies the neovasculature supplying blood to tumors." (PMID 31428651, 2019). "UCP and HIF-1α proteins were identified in one and zero out of seven non-tumor samples, respectively, while pVHL was detected in six (85%) of seven non-tumor samples." (PMID 30903204, 2019). "Hypoxia results in upregulation of hypoxia-induced factor-1α (HIF-1α) and the expression of PD-L1 on tumor cells." (PMID 31468283, 2019).
tumor (continued). "In certain types of cancer, a HIF-1α-to-HIF-2α switch evolutionarily emerges to enhance aggressive tumor growth and invasion." (PMID 31735169, 2019). "We previously reported that the exposure of tumor cells to hypoxic conditions upregulates and stabilizes HIF-1α, while ONBs are effective in reversing hypoxia and downregulating HIF-1α." (PMID 31569523, 2019). "The staining pattern for PIMO and HIF-1α were similar, implicating a discontinuous hypoxic rim at the tumor periphery." (PMID 31106146, 2019). "In tumor hypoxic conditions, tumor cells secrete HIF-1α to activate VEGF expression for angiogenesis." (PMID 31695774, 2019). "Western blot analysis using the lysates from these tumor tissues also showed that suppressed HIF-1α protein by ALM treatment, confirming that ALM blocked tumor growth by suppressing HIF-1α protein." (PMID 31083403, 2019). "HIF-1α and Bclaf1 levels were significantly higher in tumor tissues than in adjacent normal tissues, and the levels of Bclaf1 and HIF-1α were positively correlated (r = 0.9004, p < 0.01)." (PMID 30367150, 2019). "In this condition, hypoxia‐inducible factor 1α (HIF‐1α) that is a transcription factor and is known as a molecular sensor of oxygen tension plays many roles for tumor cells to adapt low oxygen levels." (PMID 31674718, 2019). "The activation of HIF-1α in the tumor context is responsible for reducing both the effect of RT and the uptake of pyrimidine analogs commonly used as chemotherapy agents to kill tumor dividing cells." (PMID 31652849, 2019). "This hypoxia triggers HIF-1α, which is known to be a detrimental factor in further modifying tumor microenvironment towards drug resistance and aberrant tissue invasion." (PMID 30746305, 2019). "Protein and total RNA were then extracted from each tumour and used to assess the expression levels of HIF-1α, FoxO1, Sesn3, MnSOD and catalase." (PMID 31905813, 2019). "After 13 days of xenograft growth in vivo, significant decreases in HIF-1α, FoxO1, Sesn3, MnSOD and catalase expression were exhibited by the tumours from the 2ME + As2O3 treatment group compared with the tumours from the control group." (PMID 31905813, 2019). "HIF-1α has been suggested to be upregulated and play an important role in tumor cells under hypoxia." (PMID 30177838, 2019). "TRIM44 stabilizes HIF-1α via deubiquitination, which is a key transcription factor that regulates MM tumor growth, angiogenesis, and bone destruction." (PMID 30089913, 2019). "The high O2 affinity of ODC-HPOCs guaranteed sufficient tumour oxygenation, which was able to break hypoxia-induced chemoresistance through inhibiting the expressions of HIF-1α, multidrug resistance 1 (MDR1) and P-glycoprotein (P-gp)." (PMID 31671658, 2019). "Both endogenous and exogenous ROS spearheads stimulation of growth factors, cytokines, and transcription factors like VEGF and HiF-1α, which promote tumor migration and proliferation through ROS-dependent cellular signaling." (PMID 31766246, 2019). "Hypoxic induced factor (HIF-1α) overexpression in tumor cells promotes the expression of vascular endothelial growth factor (VEGF), related to VM formation." (PMID 31022939, 2019). "It is widely accepted that HIF-1α contributes to radiation resistance of a large variety of tumor types by inducing cell cycle arrest, inhibiting apoptosis, promoting angiogenesis, enhancing glycolytic metabolism and suppressing ROS production by mitochondria." (PMID 30642030, 2019). "This is in line with other studies describing an increased suppressive activity of MDSC under hypoxic tumor conditions mediated by HIF-1α." (PMID 30804946, 2019). "Accumulating evidence indicates that HIF-1α protects hypoxic cells and plays an important role in regulating tumor formation." (PMID 31554859, 2019). "Our present results confirms that hypoxia-induced HIF-1α activation leads to upregulation of miR-10b-3p, which in turn facilitates tumor growth and metastasis by targeting TSGA10." (PMID 31772141, 2019).
tumor (continued). "Hypoxia, a common element in the tumor environment, leads to Hypoxia-Inducible Factor-1α (HIF-1α) stabilization to modulate cellular metabolism as an adaptive response." (PMID 31078780, 2019). "Certainly, hypoxia via HIF-1α also augments the secretion of proangiogenic cytokines in tumor cells, specifically VEGF, which is the most prominent angiogenic factor being highly expressed in a variety of different tumor types." (PMID 31572387, 2019). "Expanding UMs need to attract new blood vessels for their oxygenation, and one would expect that tumour size would, therefore, be a strong determinant of HIF1a expression." (PMID 31323773, 2019). "Under hypoxic conditions tumor cells express the hypoxia inductive factor 1-alpha (HIF-1α), which induces the overexpression of pro-angiogenic vascular endothelial growth factor (VEGF) involved in tumor progression and metastases." (PMID 31684096, 2019). "This is partially due to higher levels of HDAC4 expression in hypoxic tumor regions with increased levels of HIF1α expression, as demonstrated using IHC." (PMID 30837601, 2019). "Tumors with low oxygenation levels start to induce the expression of HIF-1α which is an important factor for tumor growth e.g. allowing the tumor cells to adapt to a hypoxic environment and regulating the production of pro-angiogenic factors." (PMID 31437208, 2019). "A study found that hypoxia contributes to the tumor immune escape by increasing the tumor cell’s expression of the metalloproteinase ADAM10 in a hypoxia-inducible factor-1 (HIF-1α)-dependent manner, leading to the increased expression of PD-L1 on tumor cells." (PMID 31533363, 2019). "HIF-1α and c-myc were significantly elevated in patients with tumor size > 2 cm, histological grade III, lymph node-positive, and TNM stage III." (PMID 31577739, 2019). "The median HIF1a messenger RNA (mRNA) expression level in the 64 tumours was 7.21 (range: 6.87–7.95)." (PMID 31323773, 2019). "It has been reported that HIF-1α is highly expressed in parenchymal tumors and that tumor growth is significantly limited after HIF-1α is knocked down." (PMID 31554859, 2019). "The negative influence of lactate on cancer prognosis in humans is most likely attributed to downstream stabilization of HIF-1α in tumor and stromal cells." (PMID 31788448, 2019). "Through various mechanisms including, but not limited to, those mediated by HIF-1α, hypoxia also leads to increased tumor proliferation and metabolic changes." (PMID 30931508, 2019). "Specifically, CA9 is considered a useful hypoxic and tumour marker and a “surrogate” of HIF-1α because its expression is induced by HIF1-α." (PMID 31142270, 2019). "HIF-1α activation has multiple collateral effects because it regulates processes as diverse as tumor growth, angiogenesis, cell proliferation, and metabolism." (PMID 31073164, 2019). "It is highly concentrated in the exosomes of OSCC cells and enhances the migratory and invasive properties of tumor cells in a mechanism that is dependent on HIF1A and HIF2A." (PMID 31110513, 2019). "Western blot analysis using the tumor tissue lysates also confirmed that HIF-1α protein was suppressed by ALM treatment in the tumors, which is consistent with the in vitro data." (PMID 31083403, 2019). "An IHC analysis of markers revealed that Ki-67, VEGFA and HIF1A expression were decreased in the corresponding tumors in tumor-bearing mice treated with bevacizumab, docetaxel, or their combination." (PMID 31018595, 2019). "In EC, high HIF-1α levels have been correlated with tumor depth of invasion, differentiation, lymphatic permeation and metastization." (PMID 31739546, 2019).